SPN (sialophorin)
Description:
Predominant cell surface sialoprotein of leukocytes which regulates multiple T-cell functions, including T-cell activation, proliferation, differentiation, trafficking and migration. Positively regulates T-cell trafficking to lymph-nodes via its association with ERM proteins (EZR, RDX and MSN) (By similarity). Negatively regulates Th2 cell differentiation and predisposes the differentiation of T-cells towards a Th1 lineage commitment. Promotes the expression of IFN-gamma by T-cells during T-cell receptor (TCR) activation of naive cells and induces the expression of IFN-gamma by CD4(+) T-cells and to a lesser extent by CD8(+) T-cells. Plays a role in preparing T-cells for cytokine sensing and differentiation into effector cells by inducing the expression of cytokine receptors IFNGR and IL4R, promoting IFNGR and IL4R signaling and by mediating the clustering of IFNGR with TCR. Acts as a major E-selectin ligand responsible for Th17 cell rolling on activated vasculature and recruitment during inflammation. Mediates Th17 cells, but not Th1 cells, adhesion to E-selectin. Acts as a T-cell counter-receptor for SIGLEC1 (By similarity). [CD43 cytoplasmic tail]: Protects cells from apoptotic signals, promoting cell survival.
Synonyms: GALGP; CD43; LSN; GPL115; LEU-22
Tractability: Antibody: its Gene Ontology location is reachable by antibodies, with high confidence; UniProt predicts a signal peptide or a membrane-spanning region; the Human Protein Atlas places it where antibodies can reach. PROTAC: UniProt records ubiquitination sites on it; ubiquitination databases record sites on it; its protein half-life has been measured.
Gene: Protein-coding gene on chromosome 16 (29,662,979 to 29,670,876, forward strand). Ensembl gene ENSG00000197471.
Subcellular location: Membrane; Cell projection, microvillus; Cell projection, uropodium; Nucleus (CD43 cytoplasmic tail); Nucleus, PML body
Subcellular location (Human Protein Atlas): Plasma membrane
Pathways (Reactome):
Hemostasis: Basigin interactions; Cell surface interactions at the vascular wall
Gene Ontology:
Molecular function: protein binding; transmembrane signaling receptor activity; heat shock protein binding
Biological process: defense response to bacterium; positive regulation of tumor necrosis factor production; T-helper 1 cell lineage commitment; cell surface receptor signaling pathway; cellular defense response; chemotaxis; establishment or maintenance of cell polarity; immune response; leukocyte tethering or rolling; negative regulation of cell adhesion; negative regulation of T cell proliferation; positive regulation of T cell migration; regulation of immune response; regulation of T cell migration; signal transduction; regulation of T cell activation
Cellular component: cell surface; extracellular exosome; extracellular region; membrane; nucleus; external side of plasma membrane; microvillus; plasma membrane; uropod; basement membrane; PML body
Genetic constraint (gnomAD): Loss-of-function variants: 6 observed, 7.57 expected, observed/expected ratio (o/e) 0.79, 90% interval 0.43 to 1.53. That is too few expected variants to judge how well the gene tolerates losing a copy. Missense variants: 517 observed, 520.11 expected, observed/expected ratio (o/e) 0.99, 90% interval 0.92 to 1.07. Synonymous variants: 201 observed, 214.52 expected, observed/expected ratio (o/e) 0.94, 90% interval 0.83 to 1.05.
Homologues: Orthologues: chimpanzee SPN (99% identical), macaque SPN (90% identical), pig SPN (55% identical), rat Spn (51% identical), mouse Spn (50% identical), guinea pig SPN (50% identical), dog SPN (45% identical), rat Spnl2 (34% identical), rat Spnl1 (33% identical).
Diseases named in the same sentence as SPN in open-access papers:
SPN is named in the same sentence as 127 diseases in open-access papers, as found by Europe PMC text mining. Sharing a sentence is not in itself a finding about the gene and the disease. The quoted sentences say what the papers report.
B-cell lymphoma (16 papers, 2012 to 2023). "While SPN is not endogenously expressed in the majority of B cell lymphomas, it is highly expressed in acute myeloid leukemia." (PMID 31882897, 2019).
breast carcinoma (9 papers, 2014 to 2025). "SPN, a gene located at locus 17q21.33, is an important tumor suppressor involved in the progression and malignancy of many tumors, including breast cancer 5-11,48." (PMID 33537097, 2021). "There are few studies regarding the regulatory role of SPN in cancers, and SPN has only been reported to be a new therapeutic target in breast cancer." (PMID 34001147, 2021). "In breast cancer, SPN plays an important role as a tumor suppressor gene." (PMID 33537097, 2021). "The downregulation of SPN in breast cancer cell lines increases the tumorigenic properties and cancer stem cell properties, such as the formation of tumorspheres and the expression of stem cell genes (NANOG, OCT4, SOX2 and KLF4), whereas the overexpression of SPN causes the opposite effect 17,18." (PMID 33537097, 2021). "Indeed, SPN might have a predictive and prognostic value not only in breast cancer but also in any type of cancer." (PMID 33537097, 2021). "Indeed, there were 5 genes that were present in our list and in the up regulated list for breast cancer (RAP2C, SPN, GINS2, ESPL1 and IRF7)." (PMID 29108258, 2017).
viral infection (6 papers, 2012 to 2025). "Our results suggest that asymptomatic viral infection prior to nasopharyngeal inoculation or experimental SPN colonisation does not increase nasal or non-nasal symptoms." (PMID 32155176, 2020).
lung carcinoma (5 papers, 2013 to 2023). "miR-939 regulates a large number of genes, such as WNT1, NTSR1, POLK, WWOX and SPN, that are related to lung cancer." (PMID 29228624, 2017). "At present, the function of SPN in the occurrence and development of lung cancer is indistinct." (PMID 34323652, 2021). "There are few studies on the DPYD, ARHGEF6, MCTP2 and SPN genes in AML, but these genes are known to be differentially expressed in other tumors, such as colorectal cancer, lung cancer and hepatocellular carcinoma." (PMID 36879313, 2023).
melanoma (4 papers, 2022 to 2026). A malignant, usually aggressive tumor composed of atypical, neoplastic melanocytes. "Analysis of differential MEs revealed module 14 (TLCD2, PRICKLE2-AS3, and SPN) was significantly upregulated by NRAS Q61L melanomas (log2fc = 100.2, adjusted p = 1.32 × 10−2) and downregulated by BRAF V600E melanomas (log2fc = −206.3, adjusted p = 3.51 × 10−14)." (PMID 39796775, 2025).
clear cell renal cell carcinoma (3 papers, 2021 to 2023). "Gao’s team found that miR-129-5p was beneficial in delaying the malignant progression of clear cell renal carcinoma by targeting the downregulation of SPN." (PMID 36591509, 2022). "Our study aims to investigate the mechanism of the miR-129-5p/SPN axis in clear cell renal cell carcinoma (ccRCC), providing a novel direction for the targeted therapy of ccRCC." (PMID 34001147, 2021). "For example, overexpression of miR-129-5P in clear cell renal cell carcinoma (CCRCC) inhibits the function of sialophorin, which eliminates the promotion effect of SPN on cell proliferation and invasion, while simultaneously inducing the cell cycle arrest of tumor cells in G0/G1 phase." (PMID 36936418, 2023).
fungal infection (3 papers, 2017 to 2020). "The NMT1/2 and MetAP2 genes’ targeting miR-132-5p was found to be associated with fungal infection of human dendritic cells with Candida albicans and Aspergillus fumigatus and regulates immune responses through the interactions with FKBP1B, KLF4, and SPN genes." (PMID 29579063, 2018).
lung adenocarcinoma (3 papers, 2013 to 2023). A carcinoma that arises from the lung and is characterized by the presence of malignant glandular epithelial cells. "The staining intensity of TNFSF14, JAM2, HGF, SPN, and LIFR in the tumors of 50 lung adenocarcinoma patients was first analyzed by immunohistochemistry and quantified according to H-scores." (PMID 36072807, 2022).
tuberculosis (3 papers, 2020 to 2025). A chronic, recurrent infection caused by the bacterium Mycobacterium tuberculosis. "For example, a 108-bp insertion in SPN was linked to tuberculosis resistance in East Asian breeds." (PMID 40564307, 2025).
acute myeloid leukemia (2 papers, 2019 to 2024). Acute myeloid leukemia (AML) is a group of neoplasms arising from precursor cells committed to the myeloid cell-line differentiation. "We noted that SPN transcript is uniformly highly expressed in acute myeloid leukemia (AML)." (PMID 31882897, 2019).
Alzheimer disease (2 papers, 2014 to 2020). A progressive, neurodegenerative disease characterized by loss of function and death of nerve cells in several areas of the brain leading to loss of cognitive function such as memory and language. "Expression change of SPN in human microglia was reported in Alzheimer's disease; Specific carbonyl level of CORO1A was reduced during the treatment to reduce Amyloid β-peptide levels in mouse model." (PMID 25379732, 2014). "Interestingly, caspase 1 and sialophorin are differentially expressed in the opposite direction after the intake of supplements compared to Alzheimer’s disease patients." (PMID 33302351, 2020).
bovine tuberculosis (2 papers, 2023 to 2024). "Because TNF-a is crucial in restricting the growth of M. tuberculosis, we speculated that the 108-bp INS in the SPN gene was related to the low susceptibility of indicine cattle to bovine tuberculosis." (PMID 37723525, 2023). "Functional investigations show that a 108-bp exonic insertion in SPN may affect the uptake of Mycobacterium tuberculosis by macrophages, which might contribute to the low susceptibility of Hainan cattle to bovine tuberculosis." (PMID 37723525, 2023). "Functional studies suggested that a 108 bp exon insertion in the sialophorin (SPN) gene may affect macrophage uptake of Mycobacterium tuberculosis, contributing to the reduced susceptibility of Hainan yellow cattle to bovine tuberculosis." (PMID 39600883, 2024).
glioma (2 papers, 2016 to 2024). A benign or malignant brain and spinal cord tumor that arises from glial cells (astrocytes, oligodendrocytes, ependymal cells). "In a cohort of 18 lower grade gliomas, in addition to the TERT promoter, OncodriveFML identifies the promoter of SPN with a highly significant FM bias." (PMID 27311963, 2016).
meningitis (2 papers, 2018 to 2020). A disorder characterized by acute inflammation of the meninges of the brain and/or spinal cord. "The improved ability of SPN:Ply-low to survive inside BMECs are also reflected in their ability to transcytose across the BBB and invade the brain in a mouse model of meningitis." (PMID 33224900, 2020).
pneumonia (2 papers, 2015 to 2021). An acute, acute and chronic, or chronic inflammation focally or diffusely affecting the lung parenchyma, caused by an infection in one or both of the lungs (by bacteria, viruses, fungi, or mycoplasma.). "Many recent studies emphasize the contribution of SPn to severe diseases such as pneumonia, bacteraemia, meningitis, and AOM, and the ability of pneumococcal conjugate vaccines to prevent them." (PMID 26423571, 2015).
bacterial pneumonia (1 paper, 2018). Acute infection of the lung parenchyma caused by bacteria (e.g., Streptococcus pneumoniae, Haemophilus influenzae, Chlamydia pneumoniae, Mycoplasma pneumoniae, and Legionella pneumophila). "To determine the ability of PR8 PB1-F2 variants to enhance secondary bacterial pneumonia, we infected mice with a non-lethal dose of 15 PFU of virus per mouse, or treated with PBS as a control, and 7 days later challenged them with a non-lethal dose of 100 CFU of SPn per mouse or with PBS." (PMID 29749408, 2018).
breast tumors (1 paper, 2021). "Our data reveal that SPN-A566V would be an event that promotes context-dependent tumorigenesis by inducing the CSC pool in breast tumors." (PMID 33537097, 2021). "SPN levels are reduced or lost in approximately 15% of breast tumors, which correlates with higher histological grade, less differentiated phenotype and worse survival." (PMID 33537097, 2021). "Moreover, tumors or cell lines with low levels of SPN showed an enrichment of CD44+ CD24- cells 17, which have been proposed to be cancer-initiating cells in breast tumors 20,21." (PMID 33537097, 2021).
dementia (1 paper, 2020). Loss of intellectual abilities interfering with an individual's social and occupational functions. "Interestingly, CASP1 and SPN are regulated in dementia and the supplemented diets in the opposite direction, indicating that the supplements may be beneficial in reducing the risk of dementia." (PMID 33302351, 2020).
endometriosis (1 paper, 2025). The growth of functional endometrial tissue in anatomic sites outside the uterine body. "Furthermore, the identification of upregulated genes, such as SIRT1, SBDS, SRF, SPN, P2RX1, TEAD3, and SLITRK3, alongside downregulated genes, including KIF22, KIF25, GAS2L2, and HINT3, highlights a broad transcriptional reprogramming within endometriosis-affected tissues." (PMID 41516028, 2025).
multiple myeloma (1 paper, 2025). "Here we extend these concepts to include tandem blockers with broader protection of normal cells and activators capable in principle of targeting blood cancers beyond AML, including NHL and multiple myeloma that express SPN." (PMID 40191207, 2025).
myonecrosis (1 paper, 2022). "New findings presented here further indicate that SPN, alone or in combination with SLO, significantly and specifically depletes a key skeletal muscle energy intermediate that could contribute to rapid muscle destruction characteristic of GAS myonecrosis." (PMID 35889195, 2022).
renal carcinoma (1 paper, 2019). A carcinoma arising from the epithelium of the renal parenchyma or the renal pelvis. "For example, renal cancer patients with higher TLCD2 expression were found to have worse survival time (Atlas); upregulated SPN expression was found to associate with better survival in endometrial, breast and melanoma cancers (Atlas)." (PMID 30949194, 2019).
upper respiratory tract infections (1 paper, 2020). "They reported that the proportion of children with SPN colonisation was higher during prompted visits for review of upper respiratory tract infections (URTI) symptoms rather than for regular planned study follow up visits." (PMID 32155176, 2020).
tumor (80 papers, 2007 to 2025). "Although tumour hypoxia is strongly associated with cancer progression and resistance to therapy, we cannot conclude whether in SPN mutation or reduced expression of KDM6A is an epiphenomenon of oxygen shortage or instead precedes the formation of a hypoxic microenvironment." (PMID 30306561, 2019). "PPP1R9B (SPN or NEURABIN‐2) is a tumor suppressor that affects tumor initiation and progression when the SPN domain that interacts with protein phosphokinase 1 (PP1) is mutated." (PMID 39778021, 2025). "Elevated SPN expression hinders the clustering of tumor cells with T cells, which reduces the effectiveness of CD3 bispecific antibody-mediated tumor cell lysis." (PMID 39796775, 2025). "The directly interaction between SIGLEC1+ macrophage and SPN+ T cell possibly expedited tumor cell lymph node metastasis." (PMID 36709495, 2023). "They interacted with the corresponding receptor CD55 and SPN and promoted tumor invasion and metastasis through the adhesion of cancer cells to normal cells." (PMID 37745301, 2023). "CSF2RA, also known as granulocyte-macrophage colony-stimulating factor receptor alpha, and CD43, also known as sialophorin or leukocyte marker, are expressed in macrophages and are involved in tumor progression." (PMID 36483544, 2022). "BiTE efficacy is in part limited by specific tumor cell phenotypes, such as the expression of sialophorin which limits T cell to tumor cell adhesion, and by similar side effects of CRS and neurotoxicity observed in CAR Therapy." (PMID 34012443, 2021). "CRISPR-mediated knockout of SPN in AML cell lines significantly enhanced tumor cell-T cell clustering and consequent tumor cell lysis." (PMID 31882897, 2019). "Our data are consistent with previous findings that SPN expression on tumor cells can limit tumor cell-T cell adhesion and T cell-mediated killing." (PMID 31882897, 2019). "CRISPR-mediated SPN knockout in AML cell lines facilitated T cell-tumor cell clustering and enhanced CD3 bsAb-mediated AML cell lysis." (PMID 31882897, 2019). "The SPN gene is located at 17q21.33, a region frequently associated with microsatellite instability, loss of heterozygosity (LOH) and a high density of well-known tumor suppressor genes, such as BRCA1 5-11." (PMID 33537097, 2021). "We used these two cells lines with different molecular expression of pRB since the role of SPN as a tumor suppression gene seems to depend on PP1 and pRB to analyze if other members of the pocket protein family could compensate pRB functions." (PMID 33537097, 2021). "In contrast, among surface markers downregulated in PAX7+ cells were CD15 (SSEA1), which may serve as a marker of tumor-propagating cells and sialophorin CD43 that mediates tumor cell-peritoneal adhesion." (PMID 34440639, 2021). "However, our work significantly extends prior studies by demonstrating the ability of SPN to limit tumor cell-T cell clustering even when cell-cell adhesion is actively promoted by a CD3 bsAb." (PMID 31882897, 2019). "While discovery and generation of glycoform-specific therapeutics is arduous, it could be an effective way to preferentially inhibit SPN function on tumor cells." (PMID 31882897, 2019). "Importantly, our data suggest that the ability of tumor cell SPN to limit T cell killing is dependent on its modification with core 2 O-glycans, which is consistent with previous findings on the anti-adhesive functions of both SPN and MUC131,32,39,40." (PMID 31882897, 2019). "The results showed that the expression of CD2, SPN, IL18, PTPRC, GZMA, and TLR7 was upregulated in the tumor group compared with the normal group (p < 0.05)." (PMID 36591509, 2022).